COX7A2 (cytochrome c oxidase subunit 7A2)
Description:
Component of the cytochrome c oxidase, the last enzyme in the mitochondrial electron transport chain which drives oxidative phosphorylation. The respiratory chain contains 3 multisubunit complexes succinate dehydrogenase (complex II, CII), ubiquinol-cytochrome c oxidoreductase (cytochrome b-c1 complex, complex III, CIII) and cytochrome c oxidase (complex IV, CIV), that cooperate to transfer electrons derived from NADH and succinate to molecular oxygen, creating an electrochemical gradient over the inner membrane that drives transmembrane transport and the ATP synthase. Cytochrome c oxidase is the component of the respiratory chain that catalyzes the reduction of oxygen to water. Electrons originating from reduced cytochrome c in the intermembrane space (IMS) are transferred via the dinuclear copper A center (CU(A)) of subunit 2 and heme A of subunit 1 to the active site in subunit 1, a binuclear center (BNC) formed by heme A3 and copper B (CU(B)). The BNC reduces molecular oxygen to 2 water molecules using 4 electrons from cytochrome c in the IMS and 4 protons from the mitochondrial matrix.
Synonyms: COX7AL; COXVIIa-L; COX7AL1; COXVIIAL; VIIAL
Tractability: Small molecule: a structure with a bound ligand is known. Antibody: UniProt predicts a signal peptide or a membrane-spanning region. PROTAC: ubiquitination databases record sites on it; its protein half-life has been measured.
Gene: Protein-coding gene on chromosome 6 (75,237,675 to 75,250,323, reverse strand). Ensembl gene ENSG00000112695.
Subcellular location: Mitochondrion inner membrane
Pathways (Reactome):
Metabolism: Complex IV assembly; Respiratory electron transport
Cellular responses to stimuli: Cytoprotection by HMOX1
Gene Ontology:
Molecular function: protein binding; protein-macromolecule adaptor activity
Biological process: cellular respiration; mitochondrial electron transport, cytochrome c to oxygen; oxidative phosphorylation
Cellular component: mitochondrial inner membrane; mitochondrial membrane; mitochondrion; respiratory chain complex IV; respiratory chain complex
Genetic constraint (gnomAD): Loss-of-function variants: 4 observed, 3.7 expected, observed/expected ratio (o/e) 1.08, 90% interval 0.51 to 1.86. That is too few expected variants to judge how well the gene tolerates losing a copy. Missense variants: 72 observed, 64.89 expected, observed/expected ratio (o/e) 1.11, 90% interval 0.92 to 1.35. Synonymous variants: 17 observed, 22.68 expected, observed/expected ratio (o/e) 0.75, 90% interval 0.51 to 1.12.
Homologues: Orthologues: chimpanzee COX7A2 (99% identical), guinea pig COX7A2 (89% identical), macaque COX7A2 (87% identical), mouse Cox7a2 (81% identical), pig COX7A2 (81% identical), rat Cox7a2 (81% identical), tropical clawed frog cox7a2 (72% identical), rat AABR07012587.1 (63% identical), zebrafish COX7A2 (57% identical), zebrafish cox7a2a (55% identical), Drosophila melanogaster COX7AL (34% identical), Drosophila melanogaster COX7AL2 (28% identical). Paralogues in human: COX7A1 (53% identical), COX7A2L (47% identical).
Diseases named in the same sentence as COX7A2 in open-access papers:
COX7A2 is named in the same sentence as 22 diseases in open-access papers, as found by Europe PMC text mining. Sharing a sentence is not in itself a finding about the gene and the disease. The quoted sentences say what the papers report.
COVID-19 (3 papers, 2023 to 2025). A disease caused by infection with severe acute respiratory syndrome coronavirus 2. "This study demonstrates that there is a persistent increased activation of nuclear-encoded OXPHOS genes namelyCOX7C, COX7A2, ATP5PO, ATP5F1C and NDUFB8 in blood tissue immediately following COVID-19 recovery, and then a time-dependent tapering off of these genes." (PMID 41141600, 2025). "Through unbiased KEGG pathway analysis of DEGs between Fga−/− and WT plasma-stimulated microglia, we identified the 12 top pathways induced by fibrinogen, including ROS (for example, Hmox1, Cox7a2, Slc25a5), COVID-19 (for example, Ccl12, Rps8, Rpl35) and AD (for example, Atp5e, Psmd2, Tubb5)." (PMID 37291385, 2023).
esophageal adenocarcinoma (3 papers, 2017 to 2020). A malignant tumor with glandular differentiation arising predominantly from Barrett mucosa in the lower third of the esophagus. "Indeed, ATP5J and COX7A2 included in our combination were also found to be downregulated and associated with response to chemotherapy, respectively in colorectal cancer and esophageal adenocarcinoma." (PMID 28545499, 2017). "A correlation has been hypothesized between alterations in mitochondrial morphology and the reduced expression of COX7A2 in esophageal adenocarcinoma patients." (PMID 29304754, 2018). "Proteomic expression profiling reveals reduction of COX7A2 (cytochrome c oxidase subunit 7A2), a subunit of ETC complex IV, which is related to patients with esophageal adenocarcinoma who respond to cisplatin plus 5-Fu therapy." (PMID 32774675, 2020).
degenerative joint diseases (2 papers, 2023 to 2024). "A GWAS analysis in humans has reported that COX7A2 and RIMS1 were identified as candidate genes for osteoarthritis, and COX7A2 was highly expressed in cartilage." (PMID 36833449, 2023).
glioma (2 papers, 2021 to 2023). A benign or malignant brain and spinal cord tumor that arises from glial cells (astrocytes, oligodendrocytes, ependymal cells). "On the other hand, aldolase C (ALDOC) and cytochrome oxidase subunit 7A2 (COX7A2), which were both negatively co-expressed genes of COL5A1, were good prognostic factors of gliomas." (PMID 34868960, 2021). "In the case of Cox7A2, which has not been well characterised in the context of cancer, the literature data available for glioma patients indicate that overexpression levels of this protein are associated with good prognosis of patients." (PMID 37377864, 2023).
amyloid (1 paper, 2025). "Cox7a2 is cytochrome c oxidase subunit 7A2 in complex IV of the ETC and catalyzes electron transfer from reduced cytochrome c to oxygen, whereby its altered expression can correlate amyloid plaque burden per AD." (PMID 40979532, 2025).
Autoimmunity (1 paper, 2022). The occurrence of an immune reaction against the organism's own cells or tissues. "As additional evidence for the contribution of mitochondrial autoimmunity to breast carcinogenesis, autoantibodies in BC sera were found to target coding and noncoding regions of the COX7A2 gene and 3′-UTR of COA4." (PMID 37082114, 2022).
dilated cardiomyopathy (1 paper, 2023). Cardiomyopathy which is characterized by dilation and contractile dysfunction of the left and right ventricles. "In another mouse study, Cox7a1 KO mice were viable and presented a dilated cardiomyopathy at 6 weeks of age with the Cox7a1 KO mice incorporating more of the “liver-type” isoform of Cox7a2 into the cardiac Cox holoenzyme, translating in higher tissue ATP levels." (PMID 37160609, 2023).
Fatal Infantile Cardioencephalomyopathy (1 paper, 2023). "In humans, the gene COX7A2 is associated with Fatal Infantile Cardioencephalomyopathy due to Cytochrome C Oxidase Deficiency (ORPHA1561), a very rare mitochondrial disease, clinically recognized by cardioencephalomyopathy resulting in death in infancy." (PMID 37160609, 2023).
glaucoma (1 paper, 2016). Increased pressure in the eyeball due to obstruction of the outflow of aqueous humor. "Beside nucleus proteins, numerous mitochondrial proteins displayed glaucoma associated level decrement, e.g. ADP/ATP translocase 3 (ANT3), pyruvate dehydrogenase component subunit ß (PDHE1-B) and cytochrome C oxidase subunit 7A2 (COX7A2)." (PMID 27425789, 2016).
Parkinson disease (1 paper, 2021). A progressive degenerative disorder of the central nervous system characterized by loss of dopamine producing neurons in the substantia nigra and the presence of Lewy bodies in the substantia nigra and locus coeruleus. "This analysis revealed that the genes implicated in Parkinson’s disease (Atp5a1, Ndufa7, Ndufb2, Ndufs8, Park7, Cox7a2, Cox7c, Cox6b1, Cycs, Uchl1) were upregulated in thia-exposed mice (p-value = 4.2E-3)." (PMID 34295895, 2021).
prostate intraepithelial neoplasia (1 paper, 2020). A neoplastic proliferation of the epithelial cells that line the acini and the ducts of the prostate gland. "It is worth noting, however, that many SV genes are not captured by t-test and that SV genes need not to be restricted to tumor vs. normal comparison a priori; e.g., COX7A2 is expressed in both tumor and prostate intraepithelial neoplasia (PIN) regions and depleted in normal prostate gland." (PMID 32103057, 2020).
schizophrenia (1 paper, 2018). A major psychotic disorder characterized by abnormalities in the perception or expression of reality. "We tested candidate genes on a cohort of schizophrenia-associated hiPSC-derived neurons and found blunted expression profiles for COX7A2, GRID2 and HOMER1 using quantitative PCR." (PMID 29691375, 2018).
cancer (5 papers, 2020 to 2026). A tumor composed of atypical neoplastic, often pleomorphic cells that invade other tissues. "Likewise, Cox7a2 expression has been used as a marker for monitoring cancer development, predicting regional lymph node metastasis, and disease outcome." (PMID 34233649, 2021). "The genes encoding the metabolic enzymes for oxidation phosphorylation such as Atp5l, Cox4i1, Cox5a, Cox7a2, Ndufc2, Ndufs4, Sdhd, Uqcrq28 were significantly downregulated in 20(S)/(R)-Rh2E2-treated LLC-1 cancer cells, but not in normal cells." (PMID 32796841, 2020).
tumor (5 papers, 2013 to 2023). "We find that as a normal tissue is transformed to a tumor tissue, overexpression of significantly short transcripts, enriched in transcripts that are involved in protein synthesis or mitochondrial metabolism (including, e.g., the transcript of the human gene COX7A2), is maintained." (PMID 24282503, 2013). "The top genes in cold tumor are ARF1, PDIA3, ALDOA, FKBP2, NDUFS5, NDUFC1, COX7A2, C14orf2, LNX1, and BTBD6." (PMID 33816503, 2021).
infection (2 papers, 2020 to 2021). The state of being infected such as from the introduction of a foreign agent such as serum, vaccine, antigenic substance or organism. "Both HIV-HSA infection and siRNA silencing of Sdha (complex II) and Cox7a2 (complex IV) significantly enhanced ROS production in primary MDMs." (PMID 34233649, 2021). "Moreover, genes involved in active metabolism like COX7A2, NDUFB6 (ILC2), NDUFA12 (ILCP), ACSL1 (NK CD16high), and DNAJA4 (NK CD56high) were upregulated in HIV-infected children, suggesting active metabolism in these subsets in response to infection." (PMID 32937142, 2020).
COX7A2 also shares sentences with these, for which no sentence is quoted: Barrett adenocarcinoma (1 paper); breast carcinoma (1); colorectal cancer (1); lung carcinoma (1); mitochondrial disease (1); Obesity (1); Sepsis (1).